IL6 (interleukin 6)
Diseases named in the same sentence as IL6 in open-access papers (continued):
Sharing a sentence is not in itself a finding about the gene and the disease.
Autoimmunity (continued). "The autoimmunity driven by IL-6 activity is believed to increase production of T-helper 17 cells (Th17) which have been strongly implicated in autoimmune myocarditis." (PMID 36851240, 2023). "Together with transforming growth factor (TGF)-β, IL-6 induces differentiation of CD4 T cells into the pro- inflammatory Th17 subsets, implicated in the pathogenesis of many autoimmune conditions." (PMID 37841263, 2023). "IL-1β has many biological functions, which are closely related to pain, inflammation, and autoimmunity, and is involved in neuroprotection, tissue remodeling and repair, and the regulation of IL-6 and TNF-α, etc.." (PMID 37109624, 2023). "Dysregulated, ongoing production of IL-6 has a detrimental impact on chronic inflammation and autoimmunity, despite the fact that its expression is tightly regulated by transcriptional and posttranscriptional processes." (PMID 38046507, 2023). "IL-6 plays critical roles in host defense, while its dysregulation also drives chronic inflammation and autoimmunity." (PMID 36726024, 2023). "The chronic phase involves cell-mediated autoimmunity, with the cytokine IL-6 playing a crucial role in the processes that lead to the degeneration of cartilage and bone." (PMID 38256854, 2023). "To conclude, it appears very unlikely that the method of action of TPE relies on or includes IL-6 removal to hamper or prevent autoimmunity." (PMID 37047524, 2023). "GAD autoimmunity could induce epileptogenic activity and increases seizure susceptibility thus initiating the activation of inflammatory pathways, both in the periphery and in the CNS, resulting in the higher production of proinflammatory cytokines such as IL-6." (PMID 37025699, 2023). "Inflammatory signaling is; however, intricate and their mediators including TNF, IL-1β, IL-6, and interferons often co-occur in conditions such as aging, cancer, and autoimmunity." (PMID 36968066, 2023). "Dysregulation of persistent synthesis of IL-6 has pathological effects on chronic inflammation and autoimmunity; for example, IL-6 induces overproduction of VEGF, leading to enhanced angiogenesis and increased vascular permeability." (PMID 36825443, 2023). "IL-6 expression is tightly regulated, therefore, it can contribute to chronic inflammation or autoimmunity, such as RA, when dysregulated." (PMID 36294967, 2022). "A variety of cytokines and chemokines play a role in the pathogenesis of RA, AS and GA by regulating inflammation, autoimmunity and joint destruction, including IL-1β, IL-6, IL-17, TNF-α, and CXCL8." (PMID 35935817, 2022). "Local injection of CFA resulted in an increase of TNF-α, IL-1β, and IL-6 levels due to activation of autoimmunity cells which aggravated complete inflammation." (PMID 35193490, 2022). "Substantial evidence further demonstrates IL-6 as a common player in autoimmunity- cancer crosstalk." (PMID 36077865, 2022). "have described the use of IL-6 blockade to reduce immunotherapy related autoimmunity (i.e. immune related enterocolitis) through the use of anti-IL-6 antibodies." (PMID 36341428, 2022). "The expression of IL-6 is strictly regulated, but persistent dysregulation of IL-6 synthesis has pathological effects on chronic inflammation and autoimmunity." (PMID 35711907, 2022). "IL-6 plays important roles in inflammatory processing—a continuation of autoimmunity via B-cell and T-helper 17 (Th17) differentiation." (PMID 35723292, 2022). "To date, most of this work has been done in murine models of autoimmunity with less known about the T cell response to IL-6 in humans." (PMID 35911690, 2022). "IL-6 plays prominent roles in chronic inflammation, autoimmunity, infectious disease and cancer and has context-dependent pro- and anti-inflammatory properties." (PMID 35625063, 2022). "Interleukin-6 is a pleiotropic cytokine, which functions range from hematopoiesis to metabolic regulation of inflammation, autoimmunity, and acute phase response." (PMID 33821263, 2021).
Autoimmunity (continued). "Streptococcus induces expression of the pro‐inflammatory cytokines TNF‐α, IL‐6, and IFN‐γ, which are associated with autoimmunity." (PMID 33970540, 2021). "The signaling axis of IL-6 is considered the central process of inflammation and autoimmunity in various tissues including pulmonary, cardiac, and joints." (PMID 34532317, 2021). "IL-6–/– and IL-23–/– mice are resistant to EAE induction, confirming the critical role of IL-6/IL-23/STAT3 signaling in CNS autoimmunity." (PMID 33411696, 2021). "The dysregulated continual synthesis of IL-6 has shown to play a pathological effect on chronic inflammation and autoimmunity." (PMID 34822503, 2021). "Overall, these results emphasize the significance of HuR in regulating the IL-6/IL-6R signaling axis in T cell activation and disease, which is in line with our recent work that HuR plays an important role in autoimmune neuroinflammation." (PMID 34395636, 2021). "IL-6 produced by B cells also contributes to the formation of spontaneous germinal centers in autoimmunity." (PMID 34040603, 2021). "IL-17 is a pro-inflammatory cytokine secreted by T helper 17 cells that act with other cytokines such as IL-1, TNF-α, and IL-6 to induce inflammatory diseases and play an important role in the development of autoimmunity." (PMID 34086720, 2021). "Although the pro-inflammatory roles of TNF and IL-12 are well-established, the immunosuppressive role of IL-6 was overlooked in autoimmunity." (PMID 34215755, 2021). "Dysregulation of the permanent synthesis of IL-6 has a pathological effect in chronic inflammation and autoimmunity." (PMID 34442410, 2021). "Long-term elevation of IL-6 levels maintains chronic inflammation and autoimmunity, making IL-6 one of the main druggable targets in autoinflammatory and autoimmune disorders." (PMID 33465050, 2021). "Th-17 cells are activated by IL-6, IL-1β, and IL-23 and trigger chronic inflammation and autoimmunity, while TGF-β and IL-6 activated Th-17 cells are weakly pathogenic and are mostly involved in tissue integrity and defense." (PMID 34067151, 2021). "Several factors that play important roles in autoimmunity are present in TA and CD, such as lymphocyte subtype and proinflammatory cytokines (IFNγ, TNFα, IL-6, IL-17, IL-18)." (PMID 33628228, 2021). "IL-6 is produced and released by muscle cells as a necessary response to infections and tissue injuries; however, unregulated synthesis of IL-6 plays a pathological role in chronic inflammation and autoimmunity." (PMID 32156094, 2020). "Since dysregulation of the TH17/Treg balance is linked to the development of autoimmunity and chronic inflammatory diseases, the induction of a TH17-type of inflammation characterizes a major pro-inflammatory function of IL-6 cis-signaling." (PMID 33334075, 2020). "Although its expression is strictly controlled by transcriptional and posttranscriptional mechanisms, dysregulated continual synthesis of IL-6 plays a pathological effect on chronic inflammation and autoimmunity." (PMID 32256705, 2020). "The CD4+ T cell-specific deficiency of gp130—and thus of IL-6-mediated signaling on T cells—leads to the abrogation of TH1 and TH17 immune responses in mouse models of autoimmunity or extracellular parasitic infection." (PMID 33334075, 2020). "Mutation in KDM6A has not previously been described as mediating the non-T cell-inflamed phenotype however KDM6A is a known epigenetic regulator of interleukin-6 and IFN-β and linked to autoimmunity." (PMID 33106165, 2020). "These pro-inflammatory cytokines, including IL-12, IL-6, and IL-23, can drive Th1 and Th17 cell differentiation and functional development, leading to inflammation and autoimmunity." (PMID 30823934, 2019). "An inhibitory mAb, Tocilizumab that binds human IL-6R and blocks its binding to IL-6 has been developed and is currently approved for the treatment of autoimmune conditions." (PMID 31491838, 2019).
Autoimmunity (continued). "Normal physiological concentrations of IL-6 are relatively low, but these are rapidly elevated in the context of infection or autoimmunity." (PMID 31699146, 2019). "The secondary chronic phase is a manifestation of cell-mediated autoimmunity and cytokine IL-6 is the principal mediator involved in the cartilage and bone degenerative process." (PMID 31450670, 2019). "High levels of circulating IL-6 demonstrate persistent systemic inflammation, and dysregulated production of IL-6 plays a key role in chronic inflammation and autoimmunity." (PMID 31323092, 2019). "IL-6 plays a role in acute phase reactions, chronic inflammation, autoimmunity, endothelial cell dysfunction, and fibrogenesis." (PMID 30809224, 2019). "Early studies revealed that IL-6 controls the proliferation and survival of Th1/Th2 cells which play a critical role in the development of autoimmunity in both human and SF mice." (PMID 31699146, 2019). "In particular, interleukin 6 participates in many biological processes such as chronic inflammation, autoimmunity, infectious diseases and cancer." (PMID 31396215, 2019). "Because activated DCs can secrete pro-inflammatory cytokines to enhance T cell autoimmunity, we determined the levels of splenic IL-12, IL-6, and IL-23 in the vehicle- and ALX-treated mice by ELISA." (PMID 30823934, 2019). "In the present study, we found elevated levels of NLRP3 inflammasome and inflammatory cytokines (IL-1β, IL-6, IL-17) in CSF in patients with autoimmune GFAP astrocytopathy." (PMID 31681133, 2019). "Th-17 cells activated by IL-6, IL-1β and IL-23 trigger chronic inflammation and autoimmunity while TGF-β and IL-6 activated Th-17 cells are weakly pathogenic and are mostly involved in tissue integrity and defense." (PMID 30744173, 2019). "IL-6 is a pleiotropic cytokine with significant functions related to the regulation of the immune system, especially autoimmunity." (PMID 30917564, 2019). "IL-6 also inhibits differentiation of T regulatory cells produced in the thymus and peripheral lymph nodes to protect against autoimmunity." (PMID 31214019, 2019). "Especially, inflammatory cytokine IL-6 signaling appears to be a key factor through which naringenin favorably influences the balance between Th17 and Treg cells, leading to an alleviated autoimmunity." (PMID 30327657, 2018). "The prototypic pro-inflammatory cytokine interleukin 6 (IL-6) is upregulated in a wide variety of immunological conditions including autoimmunity, cancer, infection and vaccination." (PMID 28953978, 2017). "TNF-α is produced at low levels in the tumor microenvironment by tumor or stromal cells, or probably both, and perpetuates chronic inflammation and autoimmunity together with IL-6, a key cytokine linking chronic inflammation to cancer." (PMID 28030810, 2017). "Taken together with previous work, our data supports a link between hypomethylated DNA within AC, IL-6 production and the development of autoimmunity in both mice and patients." (PMID 28169339, 2017). "In contrast, IL-6 can strongly inhibit the TGF-β-induced differentiation of Treg cells that inhibit autoimmunity and protect against tissue injury." (PMID 29163240, 2017). "Specific phase of this chronic and deteriorating disorder must be considered, which can involve IL-6 in acute or possible chronic inflammation and/or autoimmunity." (PMID 29163240, 2017). "In the early period of PF, inflammatory factors such as interleukin-17 (IL-17) and interleukin-6 (IL-6) play an important role in autoimmunity." (PMID 26891294, 2016). "High estrogen leads to increased Υ-interferon expression TH-1 cells and increased expression of IL-6, which is a potent mediator of autoimmunity, in T-cell." (PMID 27478827, 2016). "After immunization with myelin oligodendrocyte glycoprotein, WIM-6 mice on the C57BL/6 background exhibited intense IL6-luc luminescence in their brains and spinal cords due to autoimmunity against the myelin component (left)." (PMID 27211851, 2016).
Autoimmunity (continued). "MPO-ANCA triggers the production of IL-6, IL-17A and IL-23 and increases the activation of neutrophils, conditions that promote Th17-mediated autoimmunity." (PMID 25964886, 2015). "The role of IL-6 in regulating progressive CNS autoimmunity was assessed by treating GFAPγR1Δ mice with anti-IL-6 neutralizing antibody during chronic EAE." (PMID 25896970, 2015). "Numerous preclinical and clinical studies have revealed the pathological roles of the IL-6 pathway in inflammation, autoimmunity, and cancer." (PMID 26535093, 2015). "Th17 cells mainly regulated by Rorc produce IL-17, TNF-α and IL-6 to promote the development of autoimmunity and allergic reactions." (PMID 25873156, 2015). "The role of IL-6 in regulating progressive CNS autoimmunity was examined in the transgenic GFAPγR1Δ mouse model of progressive EAE." (PMID 25896970, 2015). "Biological agents targeting key proinflammatory cytokines, such as tumor necrosis factor alpha (TNF-α) and interleukin 6 (IL-6) have been substantially advanced in the treatment of autoimmunity." (PMID 25888920, 2015). "The functions of IL-6 in the acute phase response include chronic inflammation, autoimmunity, fibrogenesis, and endothelial cell dysfunction." (PMID 24969238, 2014). "Further, in LAG-3-deficient mice, mercury elicited higher amounts of IL-6, IL-4 and IFN-γ, cytokines known to play a critical role in mercury-induced autoimmunity." (PMID 25122007, 2014). "A set of key interleukins, namely pro-inflammatory IL-6, immunoregulatory IL-10, anti-inflammatory IL-13, and autoimmunity-related IL-17, were assayed by ELISA." (PMID 24236103, 2013). "Because the liver is known to be an important source of transforming growth factor-β and IL-6, which are cytokines that are crucial for Th17 differentiation, it is very likely that Th17 cells contribute to liver inflammation and autoimmunity." (PMID 24223606, 2013). "Among them, interleukin-6 (IL-6) is a multifunctional cytokine involved in the pathogenesis of numerous diseases, including inflammation, autoimmunity, and lymphoid malignancies." (PMID 23936794, 2013). "Investigating these connections, IL-6, IL-17, IL-10 and IL-1 cytokine activation has been demonstrated suggesting the activation of shared innate pathways in autoimmunity." (PMID 24069364, 2013). "Th17 cells expressing retinoic acid-related orphan receptor γt(RORγt) play a crucial role in the development of autoimmunity and transplant rejection, by producing pro-inflammatory cytokines IL-17, and to a lesser extent, IL-23 and IL-6." (PMID 22479627, 2012). "For example, IL-6 induces Th17 differentiation of T cells thereby contributing to autoimmunity, but it also has a neurotrophic activity shared by other gp130 cytokines." (PMID 22509390, 2012). "Th17 cells expressing retinoic acid related orphan receptor γt (RORγt) play critical roles in the development of autoimmunity and allergic reactions by producing IL-17 and IL-6." (PMID 23345934, 2012). "IL-6 is also involved in autoimmunity by altering the balance of Th17 cells by inducing the differentiation of Th17 cells from naïve CD4+ T cells." (PMID 23133751, 2012). "The cytokine transforming growth factor–β (TGF-β), in the presence of interleukin-6 (IL-6), promotes the differentiation of naïve T lymphocytes into Th17 cells, which promote autoimmunity and inflammation." (PMID 21526159, 2011). "IL-6 functions globally in response to inflammation and infection and it is important in our understanding of the development of autoimmunity." (PMID 19587788, 2009). "IL-6 acts at the crossroads of innate and adaptive immunity, influencing the differentiation of T cells into Tregs, pivotal in maintaining immune tolerance and preventing autoimmunity." (PMID 40258749, 2025). "Additionally, we found that macrophages are polarized into a proinflammatory M1 phenotype and produce IL-6 that can exacerbate inflammation and potentially lead to autoimmunity." (PMID 40943602, 2025).
Autoimmunity (continued). "Better understanding of IL-6 signaling pathways downstream of IL-6R may lead to the development of more targeted therapies to modulate inflammation and autoimmunity." (PMID 40936905, 2025). "Together, these mechanisms suggest that IL-6 may reflect the interplay between autoimmunity, metabolic dysregulation, and inflammation in T1D." (PMID 41010714, 2025). "Elevated levels of IL-6 have been frequently observed in patients with PNP and in idiopathic multicentric Castleman disease, suggesting that an imbalance of Tregs and excess IL-6 may contribute to paraneoplastic autoimmunity in the context of PNP." (PMID 39584995, 2024). "Interleukin-6 (IL-6) is a glycoprotein that is well-recognized for its role in the acute-phase inflammatory response, bone metabolism and remodeling, reproductive system, cancer progression, autoimmunity, and metabolic alterations in the liver." (PMID 38472527, 2024). "Cytokines like IL-1, IL-6, IL-18, and IL-12 are key protagonists in the start and maintenance of an inflammatory response, but stringent mechanisms of signal attenuation are essential for ensuring the avoidance of untoward effects like autoimmunity and cancer." (PMID 38533493, 2024). "An increased level of homocysteine inhibits tyrosinase and may mediate melanocyte destruction via increased oxidative damage and IL-6 production, triggering autoimmunity and nuclear factor κB activation." (PMID 39337683, 2024). "The OSM and LIF genes, members of the IL-6-related family, are pleiotropic cytokines with similar genetic structures and physiological functions that play important roles in chronic inflammation, autoimmunity, infectious diseases, and cancer." (PMID 38591204, 2024). "IL-6 is a pleiotropic master cytokine with normal physiologic functions, as well as a central role in a number of pathologic states including inflammation, infectious disease, autoimmune disorders and cancer." (PMID 38689325, 2024). "IL-6 is commonly considered a pro-inflammatory cytokine produced by classically activated macrophage 1, which has a pro-inflammatory effect on chronic inflammation and autoimmunity." (PMID 37668855, 2024). "In addition to the group of interferons, other cytokines are involved in autoimmunity, such as interleukin 6 (IL-6), known to play a fundamental role in the acute inflammatory response, hematopoiesis, and oncogenesis." (PMID 39836835, 2024). "It is tempting to speculate that Gal-4-BGA6 interactions may contribute to modulation of IL-6-dependent inflammatory responses in a wide range of immune-mediated pathologies, including autoimmune disorders, chronic infection, fibrosis and cancer." (PMID 39009340, 2024). "Furthermore, IFN hyperactivity is associated with a distinct immune profile in DS marked by elevation of acute phase proteins and key cytokines strongly tied to the development of autoimmunity, such as interleukin-6 (IL-6) and tumor necrosis factor–α (TNFα)." (PMID 37379383, 2023). "Overexpression of IL-6 has pathological effects on chronic inflammation and autoimmunity." (PMID 37189499, 2023). "Interleukin-6 (IL-6) plays a crucial role in autoimmunity and chronic inflammation." (PMID 38025060, 2023). "Interleukin 6 (IL-6) is obligated to induce T cell-mediated autoimmunity." (PMID 37752555, 2023). "From its role in blood brain permeability, antibody production by B cells, Th17 subset differentiation and effects on regulatory B cells, IL-6 has been found to be a central cytokine interfacing with the normal innate and adaptive immune system and autoimmunity." (PMID 37841263, 2023). "Subtle differences in the phenotype of the CD4+ T cells, specifically TEM cells, highlight IL-6-regulated pathways of interest, including the apoptotic pathway that may contribute to observed association of this IL6R SNP for development of autoimmunity." (PMID 35911690, 2022). "A prolonged increase of IL-6 retains chronic inflammation and autoimmunity." (PMID 35982898, 2022).